CYP24A1 (cytochrome P450 family 24 subfamily A member 1)
Diseases named in the same sentence as CYP24A1 in open-access papers (continued):
Sharing a sentence is not in itself a finding about the gene and the disease.
colorectal tumors (4 papers, 2013 to 2019). "In this search for a mechanistic explanation, increased CYP24A1 gene copy number was associated with the enzyme’s overexpression in 60 percent of colorectal tumors, and expression was correlated strongly with proliferation markers." (PMID 23463632, 2013). "We found that 77 (60%) out of 127 colorectal tumors showed increased CYP24A1 gene copy-number and that more than 6 copies of CYP24A1 correlated positively with CYP24A1 mRNA expression suggestive of a causal relationship." (PMID 23463632, 2013). "Vitamin D3 supplementation is linked to reduced tumour growth in the colon, but colorectal tumours may also overexpress the vitamin‐D‐degrading enzyme CYP24A1, potentially undermining the benefits of vitamin D intake." (PMID 26238339, 2016). "In conclusion, we demonstrate that CYP24A1 overexpression results in increased aggressiveness and proliferative potential of colorectal tumours." (PMID 26238339, 2016). "The findings warrant exploration of the effects of specific CYP24A1 inhibitors in CYP24A1‐overexpressing colorectal tumours." (PMID 26238339, 2016). "Our previous studies showed that the 1,25‐dihydroxyvitamin D (1,25‐D3) catabolizing enzyme, 1,25‐dihydoxyvitamin D 24 hydroxylase (CYP24A1) was overexpressed in colorectal tumours and its level correlated with increased proliferation." (PMID 26238339, 2016). "Recently, we observed a strong correlation between expression of CYP24A1 and the expression of proliferation markers in colorectal tumours suggesting that high CYP24A1 levels may provide a proliferative advantage to tumours." (PMID 26238339, 2016). "Furthermore, our data suggest that one of the consequences of high CYP24A1 expression in colorectal tumors is increased proliferative potential." (PMID 23463632, 2013). "We show that in a mouse xenograft model, CYP24A1 overexpression confers growth advantage to colorectal tumours, regardless of vitamin D intake." (PMID 26238339, 2016).
COVID-19 (4 papers, 2021 to 2024). A disease caused by infection with severe acute respiratory syndrome coronavirus 2. "Researchers have identified the VDBP metabolism score, CYP24A1, as significantly associated with COVID-19 severity, potentially due to the SNP rs2282679." (PMID 39272727, 2024). "A dominant mutation in rs6127099 (CYP24A1) was found to be protective of asymptomatic COVID-19." (PMID 36833234, 2023). "A further in-depth examination of the positive association between the Metabolism score (DBP, CYP24A1) and the severity of COVID-19 revealed that the polymorphism DBP rs2282679 might explain the majority of the interesting correlation found." (PMID 35392098, 2022). "Overall, the odds of asymptomatic COVID-19 are 0.32 (0.15–0.68) times for CYP24A1 (rs6127099) in AT + TT genotyped participants in comparison with AA-genotyped people adjusted for age, male gender, and Kazakh ethnicity." (PMID 36833234, 2023).
glioma (4 papers, 2019 to 2023). A benign or malignant brain and spinal cord tumor that arises from glial cells (astrocytes, oligodendrocytes, ependymal cells). "The results showed that the mRNA expression of CYP24A1 in patient‐derived glioma cell lines increased exponentially after treatment with these compounds." (PMID 37489660, 2023). "Next, we injected U251, GSC2, and GSC5 cells subcutaneously in nude mice to obtain glioma xenografts, using carbonic anhydrase IX as an acidic indicator, we examined the expression pattern of CYP24A1 in vivo." (PMID 30631035, 2019). "Results from seven normal brain tissues and 83 glioma tissues showed that CYP24A1 protein level in grade IV glioma tissues was higher than that in grade II and grade III glioma tissues." (PMID 30631035, 2019). "The authors suggested that reduced acidosis following VD3 treatment may have downregulated the expression of the CYP24A1 gene, which encodes for an enzyme responsible for the catalytic degradation of VD3 to prevent its cell modulation in these glioma cells." (PMID 35889829, 2022). "This study suggested that CYP24A1 may play an important role in malignant glioma and provided a new strategy to use CYP24A1 inhibitor and calcitriol for glioma therapy." (PMID 30631035, 2019). "We found a relatively high expression of CYP24A1 in high level glioma tissue." (PMID 30631035, 2019). "Therefore, we proved that CYP24A1 may be positively related to the malignancy of glioma and the stemness of GSCs." (PMID 30631035, 2019). "We first analyzed the expression of CYP24A1 in pH 7.4 and pH 6.8 treated U87MG-SLCs, U251-SLCs, GSC2, and GSC5 cells, as well as four normal cell lines, three glioma cell lines, and four SLCs." (PMID 30631035, 2019).
ischemic stroke (4 papers, 2020 to 2023). A stroke disorder caused by obstruction of blood flow to the brain, due to thrombotic (local blood clot formation) or embolic (due to a blood clot or other material traveling from another site) event. "The CYP24A1 rs1570669 A/G genotype reduced susceptibility to ischemic stroke in both female and male patients, while the rs2296241 A/G genotype reduced risk only in male patients." (PMID 37404714, 2023). "CYP24A1 genetic polymorphisms were also shown to be significantly associated with the occurrence of an ischemic stroke." (PMID 37601072, 2023). "Our results indicated that CYP24A1 variant (rs1570669) was associated with the decreased risk of ischemic stroke (OR = 0.60, p < .001)." (PMID 31872978, 2020). "Our results showed that the rs1570669 AG genotype in CYP24A1 was associated with a decreased risk of ischemic stroke (OR = 0.60, 95% CI = 0.46–0.80, p < .001)." (PMID 31872978, 2020). "In this case–control study, we focused on investigating the relationship of rs2762934, rs1570669, rs6068816, and rs2296241 in CYP24A1 with ischemic stroke risk." (PMID 31872978, 2020). "We firstly carried out the association analysis between four SNPs in CYP24A1 gene and ischemic stroke susceptibility in the Chinese population." (PMID 31872978, 2020). "Firstly, we just identified four polymorphisms of the CYP24A1 gene correlated with ischemic stroke risk, and more polymorphisms in CYP24A1 associated with ischemic stroke risk are needed to detect." (PMID 31872978, 2020). "It seems that age is a significant factor in association between CYP24A1 polymorphisms and ischemic stroke risk." (PMID 31872978, 2020). "We aimed to investigate the association between CYP24A1 genetic polymorphisms and ischemic stroke risk." (PMID 31872978, 2020). "The AG–AA genotype of rs1570669 in CYP24A1 gene also decreased the risk of ischemic stroke (OR = 0.68, 95% CI = 0.52–0.88, p = .003)." (PMID 31872978, 2020). "In this study, CYP24A1 SNPs effecting on ischemic stroke patients susceptibility were assessed in the Chinese Han population with case–control method." (PMID 31872978, 2020). "Notability, CYP24A1 polymorphisms (rs1570669, rs2296241, rs2762934, and rs6068816) associated with ischemic stroke risk." (PMID 31872978, 2020). "Moreover, CYP24A1 rs6068816 polymorphism was significantly associated with an increased ischemic stroke risk in age >64 years." (PMID 31872978, 2020). "Our results might give a new insight on relationship between CYP24A1 polymorphisms and ischemic stroke risk." (PMID 31872978, 2020). "CYP24A1 rs2762934 polymorphism had an enhanced susceptibility to ischemic stroke in age ≤64 years." (PMID 31872978, 2020). "Our study gave the evidences that CYP24A1 genetic polymorphisms were significantly associated with ischemic stroke patients, which would provide useful information of assessment or possible diagnostic markers for ischemic stroke." (PMID 31872978, 2020). "In age >64 years, the rs1570669 in CYP24A1 could decrease the risk of ischemic stroke (AG genotype, OR = 0.63, 95% CI = 0.40–0.99, p = .044), and also reduced the ischemic stroke risk (AG–AA genotype, OR = 0.66, 95% CI = 0.43–0.99, p = .044)." (PMID 31872978, 2020). "We guess some other polymorphisms of the CYP24A1 gene or other genes may relate to ischemic stroke with coronary disease, and it is need for further research." (PMID 31872978, 2020). "Secondly, the mechanism of CYP24A1 genetic polymorphisms influenced on ischemic stroke have not investigated in our present study, future work is required to focus on this issue." (PMID 31872978, 2020). "We have not found association between CYP24A1 polymorphisms and risk of ischemic stroke patients with coronary disease, and there were no reports about this case at present." (PMID 31872978, 2020).
kidney damage (4 papers, 2022 to 2025). "There was a 40% and 60% reduction in the mRNA level of Vdr (p < 0.05) and Cyp24a1 (p < 0.01) in ApoE KO mice with adenine-induced nephropathy." (PMID 36009040, 2022). "A reduced glomerular filtration rate (GFR) was noted not only in IH patients with recessive CYP24A1 mutations but also in patients with a heterozygous SLC34A1 variant, suggesting that elevated 1,25(OH)2D3 levels may contribute to kidney damage." (PMID 41303235, 2025). "Given the excessive toxicity related to reducing kidney Cyp24a1 activity in a mouse model of CKD, we fed VillinCreERT2Cyp24fl/fl mice and their Cre-negative controls a diet containing 0.2% adenine supplemented with 1% calcium and no vitamin D for 2 weeks to induce kidney damage (CKD diet)." (PMID 39688907, 2024).
lymph node metastasis (4 papers, 2014 to 2022). "In other studies, a positive correlation between CYP24A1 expression and the risk of vascular invasion, lymph node metastasis, tumor size, or more advanced stage of the disease was observed." (PMID 36362448, 2022). "In addition, increased CYP24A1 expression was associated with lymph node metastasis." (PMID 34298730, 2021). "CYP24A1 activity was positively correlated with tumor size, lymph node metastasis, and vascular invasion." (PMID 34298730, 2021). "CYP24A1 expression in lymph node metastases neither influenced OS nor DFS." (PMID 25334067, 2014).
preeclampsia (4 papers, 2014 to 2023). Preeclampsia is a hypertensive disorder of pregnancy that is characterized by new-onset hypertension with proteinuria presenting after 20 weeks of gestation, and depending on mild or severe forms may initially present with severe headache, visual disturbances, and hyperreflexia. "It is likely that the placental mRNA expression of CYP24A1 is dysregulated in preeclampsia and responsible for the observed seasonal differences in maternal vitamin D status." (PMID 25148115, 2014). "Decreased placental calcitriol levels seen in preeclampsia may be due to the higher degradation of this secosteroid as a consequence of increased CYP24A1 expression that has been found in preeclampsia." (PMID 26247971, 2015). "Instead, in patients with preeclampsia, a negative correlation between placental gene expression of CYP24A1 with maternal 25-OH vitamin D levels (r = −0.76, P = 0.01) was observed." (PMID 25148115, 2014). "Placental gene expression of neither CYP24A1 nor CYP27B1 nor VDR differed between seasons or between patients with preeclampsia and healthy controls (as determined by the Mann-Whitney test)." (PMID 25148115, 2014). "As the authors discuss, this might be due to the fact that CYP24A1 is active and shifts vitamin D metabolism towards inactive forms (24,25 VDH) in preeclampsia." (PMID 25148115, 2014). "In a subgroup, mRNA expression of CYP24A1 (24-hydroxylase), CYP27B1 (1α-hydroxylase) and VDR (vitamin D receptor) were quantified by real time PCR in placental samples of 14 women with normal pregnancies and 13 with preeclampsia." (PMID 25148115, 2014). "mRNA expression of placental CYP24A1, CYP27B1 and VDR (mean ± SD and (range) do not differ between patients with preeclampsia and healthy controls." (PMID 25148115, 2014). "Patients with preeclampsia displayed lower vitamin D serum levels in response to seasonal changes.The regulation of placental CYP24A1, but not of the VDR or CYP27B1 might be altered in preeclampsia." (PMID 25148115, 2014).
primary hyperparathyroidism (4 papers, 2023 to 2025). Hyperfunction of the parathyroid glands resulting in the overproduction of parathyroid hormone. "The summary of reported cases of concomitant primary hyperparathyroidism and mutations in the CYP24A1 (human cytochrome P450 24 subfamily A member 1) gene leading to impaired function of 24-hydroxylas." (PMID 38665259, 2024). "To date, 6 cases of primary hyperparathyroidism coexisting with a CYP24A1 mutation have been reported in 5 publications." (PMID 38665259, 2024). "We report a rare case of an adult with primary hyperparathyroidism and loss-of-function mutations in the CYP24A1 gene and a review of similar cases." (PMID 38665259, 2024). "The link between loss-of-function CYP24A1 mutations and the development of primary hyperparathyroidism has not been confirmed." (PMID 38665259, 2024).
type 2 diabetes (4 papers, 2007 to 2020). "Eight of these lay between PTPN1 and CYP24A1, a region of interest subject to amplification in human cancer cell lines and associated with complex traits such as type 2 diabetes." (PMID 17705864, 2007). "During type 2 diabetes progression, renal CYP24A1 is greatly elevated, impairing vitamin D metabolism and accelerating tubular injury through cellular senescence and apoptosis." (PMID 23119081, 2012).
atopic dermatitis (3 papers, 2017 to 2025). "With regard to atopic dermatitis, a polymorphism in the CYP24A1 gene has been associated with severe atopic dermatitis in adults." (PMID 28486474, 2017). "Association between the VDR and CYP24A1 polymorphisms and atopic dermatitis." (PMID 37632926, 2023). "Phenome-wide association study data suggested that modulating DGKD, CASR, CYP24A1, or SLC34A1 may result in target-mediated adverse effects including alterations in serum bilirubin, inflammatory bowel disease, migraine, atopic dermatitis, and eczematous phenotypes." (PMID 40372791, 2025).
cervical carcinoma (3 papers, 2023 to 2025). A carcinoma arising from either the exocervical squamous epithelium or the endocervical glandular epithelium. "Cervical cancer cells express an autocrine vitamin D metabolising system (VDMS) comprised of a vitamin D receptor, vitamin D catabolic enzyme (CYP24A1), and the activating enzyme of 25-hydroxycholecalciferol (25(OH)D3), CYP27B1." (PMID 36979850, 2023).
colon adenocarcinoma (3 papers, 2014 to 2020). "The hypomethylation of the CYP24A1 promoter in colon adenocarcinoma associated with significantly elevated CYP24A1 expression has also been observed." (PMID 33291213, 2020).
coronary artery disease (3 papers, 2020 to 2024). "The purpose of this research was to evaluate the contributions of CYP24A1 variants to coronary heart disease (CHD) among the Chinese Han population." (PMID 32762692, 2020). "Polymorphisms in genes associated with the regulation of calcium levels (CASR, CYP24A1, CARS, DGKD, DGKH/KIAA0564 and GATA3) and metalloproteinases (MMP-3 and MMP-9) were also associated with an increased risk of coronary artery disease and AMI." (PMID 38478535, 2024).
cutaneous squamous cell carcinoma (3 papers, 2021 to 2024). "Transfection of exosomal circ-CYP24A1 can inhibit the malignant behavior of cutaneous squamous cell carcinoma, offering new possibilities for noninvasive therapeutic strategies and potentially serving as a diagnostic marker." (PMID 38933443, 2024). "Targeting exosomal circ-CYP24A1 was found to inhibit the progression of cutaneous squamous cell carcinoma by attenuating the malignant behavior of the tumor." (PMID 35382838, 2022).
esophageal cancer (3 papers, 2014 to 2022). A primary or metastatic malignant neoplasm involving the esophagus. "CYP24A1 expression has been observed to be increased in the course of different malignancies e.g., colon, ovarian, lung, liver, or esophageal cancer." (PMID 36362448, 2022). "Similarly, esophageal cancer patients had better prognosis when the expression of CYP24A1 was lower, and the esophageal cancer cell lines with higher CYP24A1 expression showed a higher proliferation rate when compared to cell lines without CYP24A1." (PMID 25334067, 2014).
hepatoma (3 papers, 2018 to 2023). "The phenobarbital-treated human hepatoma cell line showed upregulation of CYP24A1 genes, and the dexamethasone-treated osteosarcoma cell line exhibited inhibition of VDR gene transcription." (PMID 37808100, 2023). "Interestingly, Huh7.5 hepatoma cells also express CYP27B1 and 1,25-dihydroxyvitamin D3 24-hydroxylase (CYP24A1), which converts vitamin D3 to calcitriol, afterwards to calcitroic acid, indicating that hepatocytes comprise the entire apparatus for vitamin D metabolism and activity." (PMID 29385741, 2018).
hyperparathyroidism (3 papers, 2017 to 2024). "The FGF23‐mediated effect of suppressing renal 1,25D production during CKD through activation of Cyp24a1 can have severe downstream endocrine effects, including causing hyperparathyroidism and metabolic bone disease." (PMID 35656701, 2022). "It is unclear whether the co-occurrence of PHPT with a CYP24A1 mutation in these patients is a unique coincidence or is a new phenotype of CYP24A1 mutation combined with hyperparathyroidism." (PMID 38665259, 2024). "The differential diagnosis consists in the hypocalciuric hypercalcaemia syndrome, types 2 (involving GNA11 gene) and 3 (involving AP2S1 gene); hyperparathyroidism; abnormalities of vitamin D metabolism, involving CYP24A1 and SLC34A1 genes; and reduced GFR." (PMID 28122587, 2017).
lymphoma (3 papers, 2020 to 2025). A malignant (clonal) proliferation of B- lymphocytes or T- lymphocytes which involves the lymph nodes, bone marrow and/or extranodal sites. "Significantly lower levels of CYP24A1 mRNA characterized human leukemia and lymphoma cells selected for the study compared to normal cells." (PMID 35563410, 2022). "The results showed that the level of selected miRNAs correlates with the level of proteins, especially p27, Bak1, NFκB, and CYP24A1, and miR-27b and miR-125b could be responsible for the anticancer activity of active forms of vitamin D3 in human leukemia and lymphoma." (PMID 35563410, 2022).
metabolic syndrome (3 papers, 2020). A cluster of metabolic risk factors for CARDIOVASCULAR DISEASES and TYPE 2 DIABETES MELLITUS. "DNA microarray analysis was used to investigate the kidney expression of four genes (Cyp24a1, Plin2, Calb1 and Usp2), which are reported to be involved in metabolic syndrome and LSRD." (PMID 33383715, 2020).
Non-alcoholic Fatty Liver Disease (3 papers, 2021 to 2025). "In addition, CYP24A1 polymorphisms have been implicated in non-alcoholic fatty liver disease (NAFLD) and Vit.D deficiency." (PMID 40278307, 2025).
non-small cell lung carcinoma (3 papers, 2018 to 2023). A group of at least three distinct histological types of lung cancer, including non-small cell squamous cell carcinoma, adenocarcinoma, and large cell carcinoma. "Some SNPs on VDR, GC, CYP2R1, CYP24A1, and CYP27B1 were associated with higher risk of non-small cell lung cancer (NSCLC) in Chinese people, and some SNPs on CYP2R1 and CYP27B1 were associated with the rate of FEV1 change over a ten-year period." (PMID 30249031, 2018).
osteomalacia (3 papers, 2018 to 2021). Disorder caused by an interruption of the mineralization of organic bone matrix leading to bone softening, bone pain, and weakness. "Deletion of Cyp24a1 in mice results in marked decreases in bone mineralization comparable to osteomalacia, which is rescued by also deleting the VDR, leading the authors to attribute the changes to large increases in 1,25(OH)2D." (PMID 32051922, 2020). "CYP3A4 lacks the specificity for vitamin D metabolites shown by CYP24A1, but drugs like rifampin can increase its expression leading to osteomalacia." (PMID 32051922, 2020). "For instance, the xenobiotic sensor PXR was found to bind and trans-activate two proximal VDREs in the promotor of CYP24A1, which partly explains drug-induced osteomalacia." (PMID 29489902, 2018).